ALB (albumin)
Diseases named in the same sentence as ALB in open-access papers (continued):
Sharing a sentence is not in itself a finding about the gene and the disease.
diabetes (continued). "Urine samples were collected before the induction of diabetes and at the end of 8 weeks of treatments and analyzed for urinary protein, albumin and creatinine levels." (PMID 16677399, 2006). "With regards to diabetes-related complications, a positive correlation was established between urine albumin levels and serum sialic acid using the Pearson's Correlation Test." (PMID 17187674, 2006). "Specifically, glomerular podocyte density declined early in diabetes and correlated inversely with albumin excretion rates, although the number of podocytes per glomerulus did not correlate with progression of disease." (PMID 16539708, 2006). "After adjustment for age, gender, diabetes history, headache, neurological deficits, pathogen type, and mechanical ventilation, patients in the highest BUN/ALB tertile (> 5.13) showed a 20-fold increased risk of unfavorable outcome compared to the lowest tertile (adjusted OR = 20.494, P < 0.001)." (PMID 41929452, 2026). "The study also found lower eGFR, diabetes mellitus, and low serum albumin as key predictors of CIN." (PMID 41517046, 2026). "Further analysis revealed that gender (male), hypertension, diabetes mellitus, hyperlipidemia, family history, DBP, TG, FBG, UA, NLR, MLR, and CRP/ALB were independent risk factors for the development of CHD, whereas HDL-C demonstrated an independent protective effect against CHD." (PMID 41869521, 2026). "The data collected from this study provides an interesting case where a model could be developed for predicting the development of DR using the duration of diabetes, urine albumin, CRPs, and HbA1c levels." (PMID 41541002, 2026). "Notably, NAG levels are already elevated in patients with diabetes who have a normal albumin level and a normal eGFR." (PMID 40458095, 2025). "In a Cox regression analysis, time to fragility fracture was independently associated with serum Mg <2.2 mg/dL (P < .001), in a model adjusted to age, female gender, HD vintage, diabetes mellitus, body mass index, albumin, parathyroid hormone, active vitamin D therapy and the presence of VC." (PMID 40008355, 2025). "Third, although age, smoking status, serum albumin level and diabetes history were included in the initial variable pool, they were excluded during LASSO selection because of partial information overlap with other predictors or limited incremental predictive value in the training set." (PMID 40809432, 2025). "A profile of free FA in plasma, and consequently bound to albumin, may differ in persons with diabetes compared to healthy people." (PMID 41321387, 2025). "In addition, previous studies show that increases in albumin excretion within the normal range can predict cardiovascular disease in both healthy and diabetes individuals." (PMID 40414873, 2025). "DN is typically defined by the presence of chronic kidney disease in a person with diabetes, characterized by persistently elevated levels of albumin in the urine (albumin-to-creatinine ratio ≥30 mg/g) and/or reduced kidney function (eGFR <60 mL/min/1.73 m2) for at least 3 months." (PMID 41142249, 2025). "The result of univariate analysis showed that there were significant differences in indicators such as surgery type, comorbid diabetes, number of daily food types, cereal intake, and high-quality protein intake, BMI, serum albumin and pre-albumin (all P < 0.05)." (PMID 41220716, 2025). "Ln (P/1-P) = −2.230 + 1.467 * diabetes + 0.117 * preoperative white blood cell count −0.146 * preoperative albumin + 0.001 * intraoperative blood transfusion + 0.864 * drainage tube indwelling + 0.003 * drainage volume + 0.656 * ventilator use time + 0.103 * central venous catheterization time." (PMID 40678649, 2025). "Furthermore, significant differences were found among the four groups in terms of age, sex, dialysis vintage, diabetes and cardiovascular disease, PhA, triglycerides, albumin, hs-CRP, serum phosphate, serum creatinine, and blood urea nitrogen." (PMID 41280387, 2025).
diabetes (continued). "Trace albumin is a useful biomarker for early detection of nephropathy in patients with diabetes." (PMID 39810396, 2025). "RA group have lower educational attainment, PIR (Poverty Income Ratio), have higher BMI, albumin level, TG level, and more likely to have alcohol consumers, hypertension, diabetes, cardiovascular disease, hyperuricemia and antihypertensive drugs use (P < 0.05)." (PMID 40047989, 2025). "Thus, isolated albumin molecules, carrying physiological ligands, more reliably represent a pathophysiological condition of diabetes than do purchased molecules that have been extensively modified in vitro." (PMID 41321387, 2025). "However, its accuracy can be compromised by false positives and interference from non-albumin proteins, especially in patients with conditions such as diabetes and hypertension." (PMID 40136942, 2025). "Furthermore, fewer than 50% of the patients underwent testing for urine albumin, an initial indicator of renal damage induced by diabetes." (PMID 40400440, 2025). "Additional testing can be considered as clinically indicated, including hemoglobin A1c for those with diabetes or overweight/obesity (in this case, A1c was checked given her obesity and family history of diabetes) and urine albumin to creatinine ratio (UACR) for those with CKM stage 2 and above." (PMID 40104608, 2025). "Examining the relationship between the presence or absence of symptoms and plasma uraemic toxin levels using binary logistic regression while adjusting for age, gender, albumin, and diabetes did not reveal any statistically significant associations." (PMID 40711145, 2025). "However, they exhibited higher levels of TFR, creatinine, blood urea nitrogen, urine albumin creatine ratio, hypersensitive C-reactive protein, and phosphorus, and a higher prevalence of diabetes and hypertension." (PMID 40740730, 2025). "Significant differences were observed between survivors and those who deceased in various factors, including age, race, blood urea nitrogen, albumin, neutrophil count, hemoglobin, uric acid, total bilirubin, hypertension, and diabetes mellitus (all p < 0.0001)." (PMID 40098072, 2025). "Similarly, albumin played a partial mediating role in the correlation between DSS and diabetes risk in the 70–80 years group, accounting for 8.07% (p = 0.041)." (PMID 40672414, 2025). "A limitation of our study is the small sample size (n = 20 for each group) and no validation of the possible effect concerning patient variability on the structure of albumin and the activity of bound antioxidants (e.g. grade and duration of diabetes, other comorbidities)." (PMID 41321387, 2025). "Age, gender, race, education level, marital status, BMI, smoker status, diabetes mellitus, hypertension, alcohol user, TG, TC, HDL-c, LDL-c, HbA1c, AST, ALT, albumin, eGFR, CHF, CHD, hypotensive agent, all-cause mortality and CVD mortality differed significantly across UAR quartiles (all p < 0.05)." (PMID 40386059, 2025). "In line with this, our study revealed higher C-reactive protein levels and lower albumin concentrations among diabetic individuals with low GNRI, further supporting the association between inflammation and poor nutritional state in sarcopenic diabetics." (PMID 41393007, 2025). "Independent risk factors included age (OR = 1.881, 95%CI: 1.015–3.484), hypertension (OR = 4.577, 95%CI: 2.402–8.720), diabetes (OR = 5.503, 95%CI: 2.206–13.726), Dmean_R (OR = 1.309, 95%CI: 1.155–1.483), and lactate dehydrogenase-to-albumin ratio (LAR), (OR = 1.872, 95%CI: 1.381–2.538)." (PMID 40692884, 2025). "A number of studies have suggested that early changes in glomerular filtration rate (GFR) and the presence of an elevated albumin-to-creatinine ratio (ACR) may be early indicators of diabetes-related renal problems in adolescents." (PMID 40475072, 2025).
diabetes (continued). "Furthermore, individuals in the GIB group had lower albumin and hemoglobin levels but higher creatinine and blood urea nitrogen levels, and they were more likely to have diabetes status." (PMID 40297154, 2025). "This process identified ten variables with non-zero coefficients as the most predictive features: age, gender, duration of diabetes, HbA1c (glycated hemoglobin), serum albumin, vitamin D, hyperlipidemia, hypothyroidism, alcohol history, and physical activity level." (PMID 40915183, 2025). "However, patients in the CaHMB Diabetes ONS group showed higher levels of serum albumin and HbA1c compared to the Diabetes-Specific ONS group." (PMID 41156461, 2025). "Among children and adolescents with T1D, the early increase in albumin excretion in the years following the diagnosis of diabetes may predict the subsequent increase in albumin and protein excretion." (PMID 40414873, 2025). "The results revealed that individuals with lower FT3/FT4 ratios are typically older, present higher incidences of hypertension and diabetes, lower albumin levels, reduced cardiac function, and demonstrate more widespread and intricate coronary artery anatomical abnormalities." (PMID 41451128, 2025). "Additionally, OP in the diabetes group was significantly influenced by menopause duration (B = 0.174, p = 0.009), age (B = 0.296, p = 0.007), albumin (B = 0.065, p = 0.034), and PTH (B = 0.029, p = 0.039)." (PMID 40428747, 2025). "The median albumin level was 36.00 g/L (35.79 ± 6.16 g/L), A significant portion of the PD patients had comorbid conditions: 23.09% of patients had diabetes, 77.67% had hypertension, 13.78% had a history of cardiovascular disease (CVD) events, and 10.21% had hyperlipidemia." (PMID 40416383, 2025). "Recently, glycated albumin (GA) was proposed as a novel biomarker for diabetes in dogs." (PMID 40723467, 2025). "Additionally, albumin–drug conjugates have demonstrated promising outcomes in the treatment of chronic disease, such as albumin–insulin conjugates for diabetes management, by providing prolonged glucose control." (PMID 40699702, 2025). "The XGBoost model yielded the best performance, achieving an AUROC of 0.98, and identified serum albumin, diabetes as a comorbidity, type of surgery, nutritional score and Eastern Cooperative Oncology Group (ECOG) performance status as the relevant predictive variables." (PMID 40362666, 2025). "Second, high-risk patients screened using the nomogram should receive intensified clinical monitoring, specifically through dietitian-led personalized interventions (to improve albumin and glucose levels) and tighter management of comorbidities such as diabetes and cardiovascular diseases." (PMID 41280395, 2025). "However, the Q4 had a lower proportion of diabetes and transferrin saturation, hemoglobin, albumin, calcium, phosphorus, and creatinine levels than the other groups." (PMID 40283642, 2025). "Furthermore, in rats with DKD, 6-week LI-ESWT treatment increases podocyte regeneration, renal cell proliferation and reduces diabetes-induced renal inflammation, and urinary-albumin excretion." (PMID 39934556, 2025). "Similar to the GA/HbA1c ratio, the GA correlated with BMI (r = −0.16, p < 0.0001), age (r = −0.20, p < 0.0001), haemoglobin level (r = −0.12, p < 0.005), the duration of diabetes (r = 0.21, p < 0.0001), diastolic BP (r = −0.15, p < 0.0005) and the serum albumin level (r = −0.16, p < 0.0005)." (PMID 40590067, 2025). "In addition, the studies indicate an inverse relationship between dietary intake of EPA and DHA and urinary albumin excretion (UAE) in diabetes patients." (PMID 40041714, 2025). "Among patients in the CAR >0.30 group, there is an increased representation of Black patients, poorer economic status, higher prevalence of smoking and obesity, lower eGFR, higher CRP levels and lower albumin levels, and a higher proportion of diabetes patients." (PMID 40128977, 2025).
diabetes (continued). "Albumin from persons with diabetes exposed to AAPH suffered from greater structural change than albumin from healthy persons, which could be associated with diabetes-induced modifications such as AGEs and NTs, and possibly the presence of intrinsic ligands." (PMID 41321387, 2025). "Therefore, urinary L-FABP concentration allows for detection of renal disease in patients with diabetes earlier than urinary albumin concentration." (PMID 41155157, 2025). "The association between CDAI and urine albumin levels did not exhibit a significant dependency in the subgroups of sex, age, eGFR, coronary heart disease, diabetes, and hypertension according to an interaction test (p-value for interaction <0.05)." (PMID 40225342, 2025). "Numerous variables, such as BMI, hypertension, diabetes, serum creatinine, uricacid, albumin, blood glucose, total cholesterol, triglyceride, high-densitylipoprotein cholesterol (HDL-C) and surgical type showed significant differencesacross TyG tertiles (all p < 0.05)." (PMID 40630463, 2025). "Binary logistic regression identified independent risk factors for advanced CKM in early-onset T2DM: urine albumin-to-creatinine ratio (UACR; OR = 1.077, 95% CI: 1.046–1.110), blood urea nitrogen (BUN; OR = 1.202, 95% CI: 1.005–1.436), and diabetes duration (OR = 1.102, 95% CI: 1.060–1.145)." (PMID 40937404, 2025). "Compared with the highest creatinine-cystatin C ratio group, the lowest creatinine-cystatin C ratio group had a 2.6-fold higher risk of DWFG, even after adjusting for potential confounding factors, including age, sex, diabetes mellitus, eGFR, and serum albumin." (PMID 38263396, 2024). "A 68-year-old Portuguese woman with a long-standing history of hypertension and diabetes was referred for a urine albumin–creatinine ratio of 5568 mg/g with serum albumin 3.5 g/dl, serum creatinine 1.25 mg/dl, and eGFR CKD Epidemiology Collaboration creatinine–cystatin C 32 ml/min per 1.73 m2." (PMID 39356570, 2024). "For instance, an exercise-induced increase in urinary albumin excretion rate can occur even with lighter physical activity in individuals with diabetes, in contrast to healthy peers, where such effects are typically seen only with more intense physical activity." (PMID 39472875, 2024). "The meta-analysis of eleven high-quality studies revealed that elevated BMI, diabetes, low albumin levels, malnutrition, and extended surgical duration were associated with increased infection risk, while laparoscopic procedures showed potential for risk reduction." (PMID 39193402, 2024). "An increase in urinary albumin excretion is often the first sign of renal injury in diabetes." (PMID 38247505, 2024). "Therefore, measuring glycated albumin not only provides information on blood glucose values but also indicates the progression of diabetes." (PMID 39091901, 2024). "The variables included in this dataset include demographic variables, type and duration of diabetes, clinical variables such as medication use, blood pressure and BMI and laboratory data including creatinine, urine albumin to creatinine to ratio, haemoglobin A1c and lipids." (PMID 39301450, 2024). "If the clinical circumstances make this test unfeasible, albumin excretion from a random urine sample could be a reliable alternative for evaluating kidney disease in diabetes." (PMID 38962740, 2024). "This risk persisted after adjustment for age, diabetes mellitus, and iPTH (Model 1); there was no modification after additional adjustment for dialysis vintage and albumin (Model 2)." (PMID 39335504, 2024). "After adjusting for race, gender, age, diabetes, BMI, moderate activities, uric acid, albumin, ALT, GGT, ALP, total bilirubin and creatinine, multiple logistic regression analysis indicated a positive correlation between GHR and the prevalence of NAFLD (OR = 1.22, 95% CI = 1.17–1.28)." (PMID 39296907, 2024).
diabetes (continued). "A comparison of patients undergoing HP with patients undergoing AR and APR reveals that the reasons for performing HP are multifactorial, including higher age and ASA score, lower preoperative albumin, and more frequently a history of cardiovascular disease and diabetes." (PMID 38321307, 2024). "In hemodialysis‐treated patients, it was documented that 25(OH)D level is linked to age, sex, and diabetes but not to albumin level." (PMID 38652006, 2024). "After the onset of diabetes, persistent hyperglycemia usually leads to a gradual increase in urinary albumin levels from normal to microalbuminuria and then to macroalbuminuria, followed by a steep decline in glomerular filtration rate (GFR), finally leading to ESKD." (PMID 39840000, 2024). "In addition to being a nutritional indicator, serum albumin is also a multifunctional protein related to diabetes, inflammation and thrombosis." (PMID 39807247, 2024). "It has been observed that eGlx-dependent glomerular albumin permeability is elevated in diabetes." (PMID 39201721, 2024). "Therefore, for patients with diabetes with macroalbuminuria, the treatment goal is to reduce urinary albumin by ≥ 30% to delay CKD progression." (PMID 39144629, 2024). "The data in this report confirm our previous findings of HPLBII-P being closely related to the glomerular function of diabetes mellitus, as measured by albumin excretion, and to the tubular function, as measured by the close relationships to the tubular biomarkers KIM-1 and NGAL (submitted)." (PMID 38731158, 2024). "We investigated whether the measurement of glycated albumin (GA) may be useful in detecting newly diagnosed diabetes during COVID-19 hospitalization." (PMID 38498483, 2024). "POD was significantly associated with frailty, lower preoperative MMSE scores, hyperlipidemia, diabetes, cerebrovascular disease, lower hemoglobin level, lower albumin level, longer operation time, longer CPB time, lower SctO2 at T5, and lower SctO2baseline (P < 0.05)." (PMID 39171326, 2024). "In the fully adjusted model, age, race, education, SBP, DBP, BMI, waist circumference, hypertension, diabetes, smoking status, Serum Albumin, Serum Blood Urea Nitrogen, Serum Uric Acid, eGFR, AST, HDL-C associated with the increased odds of albuminuria significantly." (PMID 38685954, 2024). "Additionally, compared with the low-ITGA1 group, the high-ITGA1 group had a longer duration of diabetes and displayed higher levels of creatinine and NT-proBNP, along with lower levels of albumin." (PMID 38413438, 2024). "These associations (with exception of HDL2-apoA-I and CETP activity) remained significant after adjustment for age, sex, BMI, smoking status, presence of diabetes, total cholesterol, creatinine level, interleukin-6 (IL-6), albumin, systolic and diastolic blood pressure, and NT-proBNP." (PMID 39244794, 2024). "On the other hand, diabetes may affect nutrient absorption and metabolism, leading to malnutrition and subsequently impacting albumin levels." (PMID 39421614, 2024). "Indeed, the evidence of older age, genotype 3, the presence of diabetes, low albumin level and platelet count, and relapse of viremia after DAA therapy remain important parameters independently associated with higher HCC incidence risk." (PMID 38793565, 2024). "It has potential as an early marker for diabetes related complications, since the association with a decrease in the glomerular filtration rate (GFR) and albumin to creatinine ratio (ACR) and progression to nephropathy in patients with diabetes have been shown." (PMID 38932813, 2024). "After adjusting for race, gender, age (Model 2), diabetes, BMI, moderate activities, uric acid, albumin, ALT, GGT, ALP, total bilirubin and creatinine (Model 3), the positive correlation was remained in Model 2 [OR = 1.41, 95% CI: (1.35, 1.47)] and Model 3 [OR = 1.22, 95% CI: (1.17, 1.28)]." (PMID 39296907, 2024).